HSPG2 (heparan sulfate proteoglycan 2)
Description:
Integral component of basement membranes. Component of the glomerular basement membrane (GBM), responsible for the fixed negative electrostatic membrane charge, and which provides a barrier which is both size- and charge-selective. It serves as an attachment substrate for cells. Plays essential roles in vascularization. Critical for normal heart development and for regulating the vascular response to injury. Also required for avascular cartilage development. In muscle, it is essential for localizing acetylcholinesterase (AChE) at the neuromuscular junctions (NMJ), most probably acting as an adapter that links the acetylcholinesterase collagenic tail peptide (COLQ) to alpha-dystroglycan, and is therefore involved in the down-regulation of colinergic synaptic transmission (By similarity). [Endorepellin]: Anti-angiogenic and anti-tumor peptide that inhibits endothelial cell migration, collagen-induced endothelial tube morphogenesis and blood vessel growth in the chorioallantoic membrane. Blocks endothelial cell adhesion to fibronectin and type I collagen. Anti-tumor agent in neovascularization. Interaction with its ligand, integrin alpha2/beta1, is required for the anti-angiogenic properties. Evokes a reduction in phosphorylation of receptor tyrosine kinases via alpha2/beta1 integrin-mediated activation of the tyrosine phosphatase, PTPN6. [LG3 peptide]: Has anti-angiogenic properties that require binding of calcium ions for full activity.
Synonyms: HSPG; PLC; perlecan; PRCAN; SJA; SJS; SJS1
Tractability: Antibody: UniProt places it where antibodies can reach, with high confidence; its Gene Ontology location is reachable by antibodies, with high confidence; UniProt predicts a signal peptide or a membrane-spanning region. PROTAC: ubiquitination databases record sites on it; its protein half-life has been measured.
Safety:
Unwanted effects reported when the protein is acted on. In parentheses: how it was acted on, where the effect was seen, and who reports it.
tardive dyskinesia (source: ClinPGx)
Gene: Protein-coding gene on chromosome 1 (21,822,244 to 21,937,310, reverse strand). Ensembl gene ENSG00000142798.
Subcellular location: Secreted, extracellular space, extracellular matrix, basement membrane; Secreted
Pathways (Reactome):
Disease: Attachment and Entry; Defective B3GALT6 causes EDSP2 and SEMDJL1; Defective B3GAT3 causes JDSSDHD; Defective B4GALT7 causes EDS, progeroid type; Defective EXT1 causes exostoses 1, TRPS2 and CHDS; Defective EXT2 causes exostoses 2; Dengue Virus Attachment and Entry; Dengue Virus-Host Interactions; RSV-host interactions; Respiratory syncytial virus (RSV) attachment and entry
Extracellular matrix organization: Degradation of the extracellular matrix; ECM proteoglycans; Formation of the dystrophin-glycoprotein complex (DGC); Integrin cell surface interactions; Laminin interactions; Non-integrin membrane-ECM interactions
Metabolism: Glycosaminoglycan-protein linkage region biosynthesis; HS-GAG biosynthesis; HS-GAG degradation
Hemostasis: Initiation of coagulation cascade; Regulation of clotting cascade
Cellular responses to stimuli: Mechanical load activates signaling by PIEZO1 and integrins in osteocytes
Metabolism of proteins: Amyloid fiber formation
Sensory Perception: Retinoid metabolism and transport
Gene Ontology:
Molecular function: protein binding; amyloid-beta binding; extracellular matrix structural constituent conferring compression resistance; low-density lipoprotein particle receptor binding; molecular adaptor activity; calcium ion binding
Biological process: brain development; cell differentiation; circulatory system development; inflammatory response; lipid metabolic process; negative regulation of angiogenesis; negative regulation of synaptic transmission, cholinergic; protein localization to synapse; receptor-mediated endocytosis
Cellular component: extracellular exosome; extracellular matrix; extracellular region; focal adhesion; basement membrane; gel phase of basement membrane; Golgi lumen; lysosomal lumen; microfibril; neuromuscular junction; neuron projection; plasma membrane; plasma membrane protein complex
Genetic constraint (gnomAD): Loss-of-function variants: 277 observed, 507.71 expected, observed/expected ratio (o/e) 0.55, 90% interval 0.49 to 0.6. The upper end of that interval is the gene's LOEUF score, 0.6, which puts it in group 2 of 6, group 1 being the genes least tolerant of losing a copy. Missense variants: 5,257 observed, 5,982.7 expected, observed/expected ratio (o/e) 0.88, 90% interval 0.86 to 0.9. Synonymous variants: 2,405 observed, 2,486.7 expected, observed/expected ratio (o/e) 0.97, 90% interval 0.93 to 1.
Gene-disease validity (ClinGen):
ClinGen rates the evidence that HSPG2 causes each of these diseases.
Schwartz-Jampel syndrome type 1 (autosomal recessive): Definitive.
Silverman-Handmaker type dyssegmental dysplasia (autosomal recessive): Definitive.
Homologues: Orthologues: chimpanzee HSPG2 (99% identical), macaque HSPG2 (96% identical), pig HSPG2 (91% identical), rat Hspg2 (86% identical), dog HSPG2 (86% identical), mouse Hspg2 (86% identical), rabbit HSPG2 (85% identical), guinea pig HSPG2 (84% identical), tropical clawed frog hspg2 (55% identical), zebrafish hspg2 (44% identical), Drosophila melanogaster trol (24% identical). Paralogues in human: LAMA5 (14% identical), LAMA3 (13% identical), LAMA1 (13% identical), LAMA2 (13% identical), USH2A (11% identical), AGRN (9% identical), LAMC1 (8% identical), LAMC3 (8% identical), LAMB1 (7% identical), LAMA4 (7% identical), LAMB2 (7% identical), LAMB4 (7% identical), and 15 more.
Diseases named in the same sentence as HSPG2 in open-access papers:
HSPG2 is named in the same sentence as 133 diseases in open-access papers, as found by Europe PMC text mining. Sharing a sentence is not in itself a finding about the gene and the disease. The quoted sentences say what the papers report.
Schwartz-Jampel syndrome (14 papers, 2014 to 2024). "Schwartz-Jampel Syndrome is an autosomal recessive disorder with one affected allele of the HSPG-2 gene that results in less than 10% of functional perlecan levels in the skeletal muscle, fibroblasts, heart and the kidney." (PMID 37324385, 2023). "Two diseases arise from frameshift mutations within the HSPG-2 gene, including the heterozygous and milder chondrodysplasia, Schwartz-Jampel Syndrome, and the homozygous neonatal lethal disorder, Silverman-Handmaker Dyssegmental Dysplasia." (PMID 37324385, 2023). "Mutations in the perlecan gene (HSPG2) have been identified in two classes of musculoskeletal conditions in the relatively mild Schwartz-Jampel syndrome and more severe but relatively rare neonatal lethal dyssegmental dysplasia, Silverman-Handmaker type." (PMID 35433700, 2022). "Mutations in HSPG2 have been associated with Schwartz-Jampel Syndrome (SJS) and Dyssegmental Dysplasia Silverman-Handmaker Type (DDSH), two disorders characterized by skeletal abnormalities." (PMID 33678174, 2021). "Conversely, in the Schwartz-Jampel syndrome (SJS) with proven biallelic mutations of HSPG2 the needle EMG shows complex repetitive discharges of constant amplitude and frequency, with abrupt discontinuation of the burst." (PMID 32117035, 2020). "Mutations in the HSPG2 gene have been observed in patients with Schwartz-Jampel syndrome (chondrodystrophic myotonia), which is an autosomal recessive disorder characterized by bone dysplasia and myotonia." (PMID 30283332, 2018). "Although rare, mutations in HSPG2 are associated with two classes of human skeletal disorders, known as Schwartz-Jampel syndrome (SJS; OMIM #255800) and dyssegmental dysplasia, Silverman-Handmaker type (DDSH; OMIM #224410)." (PMID 30453502, 2018). "For instance, mutations in HSPG2 gene can cause the autosomal recessive conditions Schwartz-Jampel syndrome type 1 (SJS1) and Silverman-Handmaker type of dyssegmental dysplasia." (PMID 28327142, 2017). "Homozygous HSPG2 mutations could lead to a more severe phenotype in human disease, such as Schwartz- Jampel syndrome Type 1 and Dyssegmental Dysplasia, Silverman-Handmaker Type." (PMID 30646882, 2019). "Mutations within the HSPG2 gene have been associated with two human diseases transmitted in an autosomal recessive pattern of inheritance, Schwartz-Jampel syndrome, type 1 (SJS1) [MIM: #255800] and dyssegmental dysplasia Silverman-Handmaker type (DDSH) [MIM: #224410]." (PMID 25504735, 2014). "Previous studies have shown that homozygous mutations in the HSPG2 gene lead to pathological outcomes in two rare genetic disorders affecting the musculoskeletal system: Schwartz-Jampel syndrome (SJS) and dyssegmental dysplasia, Silverman-Handmaker type (DDSH)." (PMID 39680213, 2024). "The diseases related to HSPG2 mutations mainly include dyssegmental dysplasia Silverman-Handmaker type (DDHS) and Schwartz Jampel syndrome type 1, both of which are autosomal recessive diseases." (PMID 36123715, 2022). "HSPG2 is an essential gene, and its mutations could lead to Schwartz-Jampel syndrome, type 1(SJS) and severe neonatal lethal Dyssegmental dysplasia, Silverman-Handmaker type (DDSH)." (PMID 33777089, 2021). "In contrast, Schwartz-Jampel Syndrome (SJS, OMIM#255800) patients with mutations in the HSPG2 gene that reduce perlecan levels display a less severe phenotype with short stature, kyphosis, skeletal dysplasia, and myotonia." (PMID 32013135, 2020).
breast carcinoma (10 papers, 2017 to 2024). "MiR-663, when hypomethylated, has been shown to induce chemoresistance in breast cancer cells by targeting heparin sulfate proteoglycan 2 (HSPG2)." (PMID 38919953, 2024). "TNBC with increased SD on PrecontrastT1 showed a 23-fold, 13-fold, sevenfold, fivefold, and fivefold upregulation of CLEC3A, SRGN, HSPG2, KMT2D, and VMP1 respectively, and these genes are associated with poor survival in breast cancer." (PMID 37391754, 2023). "This was complemented through an observation showing elevated miR-663 regulated chemoresistance by decreasing HSPG2 expression in breast cancer cells." (PMID 36934129, 2023). "Overexpression of hypomethylated miR-663 induces chemoresistance in breast cancer cells by down-regulating HSPG2." (PMID 32850327, 2020). "Importantly, intense staining of malignant cells was observed in breast cancer-derived liver, lung and lymphatic metastases, pointing to the continued expression of HSPG2 in metastatic cells." (PMID 31462656, 2019). "Likewise, hypomethylation and concordant overexpression of miR-663 reduces the drug sensitivity of human breast cancer cells by repressing the expression of heparan sulfate proteoglycan 2 (HSPG2)." (PMID 28467812, 2017). "However, HSPG2 expression in breast cancer has not been examined comprehensively." (PMID 31462656, 2019).
prostate carcinoma (9 papers, 2015 to 2025). A carcinoma that arises from epithelial cells of the prostate gland. "In addition, elevated levels of HSPG2 fragments were identified in the sera of patients with invasive prostate cancer and associated with increased secretion of MMPs." (PMID 32764784, 2020). "Another study reported that M2 macrophages increase the transcription levels of SULF1 and HSPG2 in bone marrow fibroblasts and affect the microenvironment of prostate cancer bone metastasis." (PMID 36612128, 2022). "A similar decrease in proliferation occurred in melanoma, Kaposi’s sarcoma cell lines and more recently in prostate cancer cells in vitro and in vivo, following HSPG2 downregulation using antisense." (PMID 31462656, 2019). "HSPG2 showed enhanced expression in intrahepatic cholangiocarcinoma and promoted prostate cancer cell viability and proliferation." (PMID 29179459, 2017). "HSPG2 was also reported to regulate immune and stromal infiltration in glioma and prostate cancer." (PMID 35884556, 2022).
Myotonia (7 papers, 2015 to 2024). An involuntary and painless delay in the relaxation of skeletal muscle following contraction or electrical stimulation. "SJS results from partial loss-of-function mutations in the HSPG2 gene, leading to myotonia, chondroplasia, and neuromuscular deficits." (PMID 39680213, 2024). "Recently, a patient with DDRD was reported to have a mutation in HSPG2, and the presence of myotonia was suggested; however, joint contracture made the evaluation of muscle symptoms difficult." (PMID 36979792, 2023). "A monoallelic variant of HSPG2 was identified in our patient, and while we cannot exclude the possibility of a modifier effect that exacerbates myotonia from the sodium channel L796V defect, we think this is unlikely for several reasons." (PMID 32117035, 2020). "Myotonia related to SJS is not based on an ion channel defect, but on mutation of HSPG2, the perlecan." (PMID 32648012, 2020).
glioma (6 papers, 2017 to 2023). A benign or malignant brain and spinal cord tumor that arises from glial cells (astrocytes, oligodendrocytes, ependymal cells). "HSPG2, in glioma tissues, is related to the transformation of the brain extracellular matrix into the tumour microenvironment and represents a negative prognostic factor in overall and relapse-free survival." (PMID 34316711, 2021). "In this study, we found that heparan sulfate proteoglycan 2 (perlecan) (HSPG2), syndecan-1 (SCD1), clathrin (CLTC), and dynamin (DNM1) were present in all patient-derived glioma cells." (PMID 36992317, 2023). "It was found that ASPM, CCNB2, HSPG2, KLHDC8A and RRM2 mRNA were differentially expressed in glioma tissues of different grades." (PMID 32667745, 2020).
Obesity (6 papers, 2020 to 2025). Accumulation of substantial excess body fat. "Besides, perlecan (HSPG2, Heparan Sulfate Proteoglycan 2) was found to regulate obesity and lipid deposition." (PMID 32847498, 2020). "It is thus not surprising that perinatally rescued Hspg2-deficient (Hspg2–/–tg) mice are resistant to diet-induced obesity due to reduced AT hypertrophy." (PMID 32508807, 2020). "This analysis identified proteins not previously associated with childhood obesity, to the best of our knowledge, including A2M, PON3, ADAMTSL4, HSPG2 and MAGEB6B, all of which showed decreased levels in children with obesity." (PMID 39972214, 2025). "This prospective, case-control study evaluated the impact of obesity on oocyte quality based on mtDNA expression in cumulus cells (CC), and on bone morphogenetic protein 15 (BMP-15) and heparan sulfate proteoglycan 2 (HSPG2) in follicular fluid (FF)." (PMID 39594620, 2024). "This study evaluated the impact of obesity on oocyte quality using three main factors that reflect oocyte quality: mtDNA levels in CC, and levels of BMP-15 and HSPG2 in FF." (PMID 39594620, 2024). "BMI-predictive proteins included established obesity markers and obesity-related proteins, including adiponectin, CRP, IGFBP1, IGFBP2, PRG4, SHBG, apolipoproteins (APOA4, APOF) and inflammatory response proteins (A2M, APCS, LBP, HSPG2, HP, AOC3, ITGB1, VNN1)." (PMID 39972214, 2025).
acute myeloid leukemia (5 papers, 2020 to 2025). Acute myeloid leukemia (AML) is a group of neoplasms arising from precursor cells committed to the myeloid cell-line differentiation. "High HSPG2 expression levels negatively correlate with the survival of patients suffering from acute myeloid leukemia." (PMID 40146858, 2025). "However, very little is known about the effect of HSPG2 on acute myeloid leukemia (AML)." (PMID 32606327, 2020).
cervical carcinoma (5 papers, 2023 to 2025). A carcinoma arising from either the exocervical squamous epithelium or the endocervical glandular epithelium. "In cervical carcinoma, the most immunogenic epitopes were found in proteins expressed by HSPG2 and MUC5AC." (PMID 41471728, 2025). "In our model, HSPG2 is thought to be a protective factor against cervical cancer." (PMID 38455474, 2024). "This TvAP65-SPCS1-CD151/HSPG2 axis highlights potential therapeutic targets to disrupt the synergy between HPV and T. vaginalis, offering new strategies for cervical cancer prevention." (PMID 41199321, 2025).
chondrodysplasia (5 papers, 2015 to 2025). "Two rare chondrodysplasias, SJS1 and DDSH, are due to autosomal recessive mutations in the HSPG2 gene." (PMID 35537467, 2022). "Intriguingly, some mouse models which alter levels of perlecan expression mimic the clinical phenotype seen in severe chondrodysplasia disorders, including the embryonic lethal HSPG2 knock-out disorder, DDSH, and the HSPG2 knock-down disorder known as SJS." (PMID 37324385, 2023). "In mice, a specific mutant HSPG2 strain (C1532Yneo) was described to have reduced body weight and to develop chondrodysplasia and hip dysplasia." (PMID 28327142, 2017). "Very early on, Hspg2-null mice indicated perlecan’s central role in chondrodysplasias." (PMID 35537467, 2022). "HSPG2 mutations in humans cause dyssegmental dysplasia, a lethal autosomal recessive disorder accompanied by short-limbed dwarfism, as well as nonlethal chondrodysplasia and early onset osteoarthritis." (PMID 40146858, 2025).
atherosclerosis (4 papers, 2013 to 2025). A disease characterized by the build-up of fatty material and calcium deposition in the arterial wall resulting in partial or complete occlusion of the arterial lumen. "HSPG2 is implicated in various pathological processes, such as tumor development, osteoarthritis, muscle hypertrophy, atherosclerosis and diet-induced obesity." (PMID 32508807, 2020). "HSPG2 binds growth factors and connects proteins in the plasma membrane with fibers of the extracellular matrix, such as collagen and laminin, and it has been suggested to play a role in numerous diseases including atherosclerosis, cancer metastasis and Alzheimer’s disease." (PMID 40146858, 2025). "circRNAs from HSPG2 and YPEL2 in blood PBMC samples detected atherosclerosis with an AUC of 0.73." (PMID 39901821, 2025). "A specific set of circRNAs was capable of distinguishing atherosclerotic from healthy arterial tissue in individual patients, and circRNAs from YPEL2 and HSPG2 served to distinguish patients with atherosclerosis from non-atherosclerosis individuals by blood sampling." (PMID 39901821, 2025).
pancreatic cancer (4 papers, 2019 to 2025). "In pancreatic cancer, tumor cells epigenetically reprogram CAFs that promote HSPG2 release through an NF-κB-dependent pathway, increasing invasion, metastasis, and chemoresistance to gemcitabine." (PMID 35887248, 2022). "Lastly, stromal deposition of HSPG2 in a cohort of KPflC and KPC pancreatic tumors was assessed via IHC staining." (PMID 31406163, 2019).
Sepsis (4 papers, 2013 to 2025). Sepsis is defined as life-threatening organ dysfunction caused by a dysregulated host response to infection. "Genes and pathways related to cardiac and vascular function were upregulated, such as MYOZ3 and HSPG2, which may reflect hyperdynamic cardiac function and vascular dysregulation during sepsis." (PMID 40806258, 2025). "For sepsis prognosis, five proteins were significantly up-regulated: selenium binding protein-1, heparan sulfate proteoglycan-2, alpha-1-B glycoprotein, haptoglobin, and lipocalin; two proteins were significantly down-regulated: lysosome-associated membrane proteins-1 and dipeptidyl peptidase-4." (PMID 23372690, 2013).